RNU6-248P (RNA, U6 small nuclear 248, pseudogene)
Gene: Small nuclear RNA gene on chromosome 6 (76,092,834 to 76,092,940, forward strand). Ensembl gene ENSG00000222652.
Homologues: Orthologues: chimpanzee U6 (98% identical), macaque U6 (90% identical). Paralogues in human: RNU6-517P (82% identical), RNU6-1316P (81% identical), RNU6-20P (81% identical), RNU6-1145P (80% identical), RNU6-151P (80% identical), RNU6-19P (80% identical), RNU6-38P (80% identical), RNU6-393P (80% identical), RNU6-726P (80% identical), RNU6-1024P (79% identical), RNU6-1031P (79% identical), RNU6-1317P (79% identical), and 1288 more.